BCRP3 (BCR pseudogene 3)
Synonyms: formerly BCR3; BCRL6; BCRL3
Gene: Transcribed unprocessed pseudogene on chromosome 22 (24,644,791 to 24,650,832, forward strand). Ensembl gene ENSG00000284128.
Diseases named in the same sentence as BCRP3 in open-access papers:
BCRP3 is named in the same sentence as 6 diseases in open-access papers, as found by Europe PMC text mining. Sharing a sentence is not in itself a finding about the gene and the disease. The quoted sentences say what the papers report.
colorectal cancer (1 paper, 2022). A primary or metastatic malignant neoplasm that affects the colon or rectum. "While overexpression of BCRP3 in HCT116 human colorectal cancer cell line did not affect cell viability at the basal state, it significantly increased cell viability upon treatment with a chemotherapeutic drug 5-FU." (PMID 35538574, 2022).
cancer (1 paper, 2022). A tumor composed of atypical neoplastic, often pleomorphic cells that invade other tissues. "By analyzing TCGA data sets, we identified lncRNA BCRP3 based on its lower expression in tumor than normal tissues in many cancer types, including colon, esophagus, brain, skin, stomach, testis, kidney, lung, ovary, prostate, and liver." (PMID 35538574, 2022). "The downregulation of BCRP3 in many cancer types suggested its role in tumor suppression." (PMID 35538574, 2022).
metabolic disorders (1 paper, 2024). "The role of LOC124905962, EXOC3L4, BP11-795H16.2, and BCRP3 in metabolic disorders has not been well-documented yet." (PMID 38997780, 2024).
tumor (1 paper, 2022). "BCRP3 was identified based on its downregulation in many types of tumor tissues, compared with the normal tissues." (PMID 35538574, 2022). "However, whether BCRP3 plays a suppressive role in tumor initiation through its autophagy-enhancing function remains unclear." (PMID 35538574, 2022). "Studying the tumor-initiation function often requires the utilization of genetically modified mouse models, but the lack of murine homologue of BCRP3 precludes such study." (PMID 35538574, 2022).
BCRP3 also shares sentences with these, for which no sentence is quoted: lung adenocarcinoma (1 paper); lymph node metastasis (1).